BRCA1 (BRCA1 DNA repair associated)
Diseases named in the same sentence as BRCA1 in open-access papers (continued):
Sharing a sentence is not in itself a finding about the gene and the disease.
cancer (continued). "Our analysis of genomic data from 31,927 patients with matched germline and tumor sequencing from a variety of cancer histologies reveals BRCA1/2 reversion mutations across BRCA-associated tumor types." (PMID 36418296, 2022). "MiR223-3p is a negative regulator of the NHEJ DNA repair and represents a therapeutic pathway for BRCA1- or BAP1-deficient cancers." (PMID 35328651, 2022). "BRCA1 is also rendered inactive in some cancers via BRCA1 promoter hypermethylation; it is likely that loss of BRCA1 methylation during or before treatment can also result in an effective reversion of the HR phenotype." (PMID 35567571, 2022). "The association results and estimated age-specific risks will improve the cancer risk management for men and women with BRCA1/2 PVs." (PMID 35077220, 2022). "Previous studies described an association between reduced BRCA1 mRNA or protein levels and responsiveness to cisplatin therapy in different types of cancer." (PMID 35203410, 2022). "The goal of this paper is to show methods and examples of fertility counselling for BRCA1/2 gene mutation carriers, including both patients already affected by cancer and healthy individuals." (PMID 35887761, 2022). "BRCA1 c.5407-25T>A was identified in siblings both having OC (one diagnosed with a HGSC of the ovary and the other with primary peritoneal carcinomatosis), cancer phenotypes consistent with harboring a BRCA1 or BRCA2 pathogenic variant." (PMID 35456503, 2022). "PARPis are increasingly being used to treat human cancers, particularly for tumors with BRCA1/2 mutations or BRCAness; however, the development of acquired resistance limits their use in the clinic." (PMID 35847859, 2022). "PARP inhibitors are designed to inhibit auto-PARylation by competitively binding to PARPs at the NAD+ binding site, leading to cell death in BRCA1/2-mutated cancer cells through a synthetic lethality mechanism." (PMID 36209184, 2022). "The rationale for this approach is supported by evidence that BRCA1/2-deficient cancers express higher levels of neoantigens, thereby increasing immunogenicity." (PMID 35681599, 2022). "Mutations or defects in the BRCA1 gene significantly increase the risk of breast, ovarian, prostate, and other cancers in carriers." (PMID 35300412, 2022). "In summary, we performed a genome-wide screening of metastatic repressors and identified ATP11b as a potent metastasis suppressor for Brca1-deficient cancers, as its knockout enhances tumor metastasis in vivo." (PMID 35025764, 2022). "DNA damage response inhibitors are widely used anti-cancer agents that have potent activity against tumor cells with deficiencies in various DNA damage response proteins such as BRCA1/2." (PMID 36276148, 2022). "The results are the following distribution of cancer-associated mutations in genes: BRCA1 (31.4%), BRCA2 (12.2%), CHEK2 (10.5%) and other HCPS genes (45.9%), which is similar to our data." (PMID 36290365, 2022). "The personal and family history of cancer in case 2 already led in 2011 to the identification of the pathogenic BRCA1 germline variant NM_007294.3(BRCA1_v001):c.3756_3759del (p.Ser1253Argfs*10)." (PMID 35280729, 2022). "BRCA1/2 mutations were associated with a higher stage and higher grade of disease when compared with other cancer‐associated gene mutations (p value = .045 & .028)." (PMID 35608067, 2022). "Polygenic risk scores (PRS) that combine the effects of multiple disease-associated single nucleotide polymorphisms (SNPs) provide marked cancer risk stratification in the general population and BRCA1 and BRCA2 carriers." (PMID 34320204, 2022). "In mouse models of TNBC proficient or deficient of breast cancer type 1 susceptibility gene (BRCA1), MYC overexpression dramatically decreases lymphocyte infiltration in tumors, along with immune signature remodelling." (PMID 36323660, 2022). "BRCA1 variant carriers were more likely to be early onset of BC, with a positive family history of any cancer and TN phenotype." (PMID 36232564, 2022).
cancer (continued). "Ovarian tissue freezing should be used in BRCA1/2 gene mutation carriers with particular caution due to the possibility of ovarian transplantation with developing cancer." (PMID 35887761, 2022). "The usage of PARPi, which predominantly blocks the activity of PARP1, PARP2 and PARP3, is a well-established example of synthetic lethality-based therapy in BRCA1/2-mutated cancers with a limited toxicity towards normal cells and tissues." (PMID 36497275, 2022). "The accurate detection of somatic allelic imbalances (AIs) has been limited by methods focused on BRCA1/2 mutations and using mixtures of cancer types." (PMID 36581696, 2022). "The cancer-prone diseases, like those associated with BRCA1/BRCA2 mutations, are systematically associated with hyper-recombination." (PMID 35301607, 2022). "Although the germline nature of BRCA1 mutation determines that the mutation is inherited at fertilization, it can take decades for the mutated BRCA1 to transform normal cells into cancer cells." (PMID 35869059, 2022). "This was performed to identify a driving factor to initiate the mammary tumorigenic process, as inherited mutations in BRCA1 are known to cause specific molecular and cellular alterations in breast tissue even before cancer development." (PMID 35327946, 2022). "As expected, germline BRCA1/2 rates were significantly higher in BRCA-associated cancers (overall 5.5%; ovarian 9.6%; pancreatic 5.2%; breast 4.9%; prostate 4.5%) compared to rates in non-BRCA-associated histologies (1.4%) (P < 0.001, Fishers exact test)." (PMID 36418296, 2022). "Of the patients, 73.2% underwent genetic testing, and 30% of them presented germline likely pathogenic or pathogenic variants in cancer predisposition genes (24 BRCA1, 4 BRCA2, 1 PALB2, 1 NBN, and 1 ATM)." (PMID 36531080, 2022). "In the case of BRCA1 c.5057A>C (p.His1686Pro), we reported a strong association to cancer-affected members of the family." (PMID 36741700, 2022). "BRCA1-associated cancers with positive TRα had an inferior prognosis compared to counterparts that were negative for TRα expression." (PMID 35160139, 2022). "The p.Arg1726fs variant of BRCA1 has been found in more than 30 individuals with BRCA1-related cancers." (PMID 35950060, 2022). "Here, we aimed to identify novel candidate BC predisposition genes and variants by performing WES on germline DNA from Asian BC patients referred for cancer genetic risk assessment but who were BRCA1/2-negative." (PMID 36424660, 2022). "Women who carry deleterious BRCA1/2 mutations are recommended to undergo prophylactic risk-reducing surgery to decrease cancer-related mortality." (PMID 36672847, 2022). "BRCA1-deficient cancer cells exhibit impaired repair of double-strand breaks (DSBs) by the error-free mechanism of homologous recombination (HR)." (PMID 35387978, 2022). "One mechanism that has been confirmed in patients with BRCA1- or BRCA2-mutated cancers is the occurrence of secondary mutations in the BRCA1 or BRCA2 genes, leading to HR restoration." (PMID 36467895, 2022). "The ongoing phase II MEDIOLA trial is evaluating the efficacy of the PD-L1 inhibitor durvalumab and the PARP inhibitor olaparib in cancers with BRCA1 /2 mutations, with results showing a 12-week DCR of 80%." (PMID 36478716, 2022). "In general, we demonstrate that cAMP promoted by ADRB1 abolishes cell cycle arrest and DNA damage induced-apoptosis in BRCA1-deficient cancer cells." (PMID 35517499, 2022). "The purpose of this analysis was to identify predictors of cardiopulmonary fitness (VO2peak) in cancer-unaffected and cancer-affected BRCA1/2 mutation carriers." (PMID 35190584, 2022). "This study investigates the associations between the risks of 22 cancers and BRCA1/2 PVs using data from 5,341 families segregating BRCA1 or BRCA2 PVs." (PMID 35077220, 2022).
cancer (continued). "Currently, the most effective means of cancer prevention in BRCA1/2 mutation carriers entails surgical removal of the organs at risk." (PMID 35701800, 2022). "BRCA status can impact on preventive options according to the cancer spectrum related to BRCA1 or BRCA2 pathogenetic variants." (PMID 35454911, 2022). "These BRCA1/2 mutations impair homologous recombination function of cancer cells, which lead to accumulation of DNA double strand breaks caused by inhibition of PARPs." (PMID 35372044, 2022). "Although linkage studies have been utilized for the identification of variants associated with cancer in the world, little is known about their role in non BRCA1/2 individuals in the Sri Lankans." (PMID 35655316, 2022). "For BRCA-associated malignancies, patients harbor a germline BRCA1/2 mutation in one allele throughout all cells, then lose the second allele exclusively within cancer cells as an obligate step of carcinogenesis." (PMID 35205750, 2022). "Accurate assessment of the clinical relevance of a given BRCA1 variant is crucial for risk assessment, genetic counselling, and clinical management including cancer prevention in both the patient and healthy relatives with the same hereditary predisposition." (PMID 34981296, 2022). "Ultimately, these results suggest key biological features of therapy-resistant recurrences, thereby highlighting therapeutic possibilities for BRCA1/2 mutation carriers with cancer." (PMID 36344544, 2022). "Considering all these findings, we decided to evaluate the potential therapeutic impact of OGG1 inhibition on BRCA1-deficient cancer cells as well as its interaction with PARP inhibition." (PMID 35619904, 2022). "The secreted DKK1 from BRCA1-deficient cancer cells on the other hand confronts immune cells, assisting the apoptotic resistance." (PMID 35517499, 2022). "Transition probabilities were calculated based on real-world data of women tested for BRCA1/2 germline mutations in a cancer reference hospital from 2011 to 2020." (PMID 35898894, 2022). "G4-stabilizing drugs have been used for cancer treatment, and they exhibit more toxic effects in BRCA1/2-deficient and ATRX-deficient cancer cells." (PMID 36470428, 2022). "Mutations within the RING domain of E3 ligases such as BRCA1 are correlated with high risk of cancer." (PMID 35281275, 2022). "More recently, the use of enlarged genomic testing in cancer patients has shown that MUTYH monoallelic variants are identified in BRCA1/2-negative BC patients, even if with a frequency similar to that of the expected carrier frequency." (PMID 36035419, 2022). "Detection of BRCA1/2 germline mutations is necessary for diagnosing and prophylactically preventing several types of cancers, especially those of the breast, ovary and prostate." (PMID 35753294, 2022). "A landmark achievement based on synthetic lethality in cancer was the discovery of poly (ADP-ribose) polymerase (PARP) inhibitor in BRCA1/2 mutated ovarian cancer." (PMID 36123603, 2022). "We identified breast cancer type 1 (BRCA1) as a potential keloid-associated gene by integrating gene expression and cell experiments." (PMID 36015648, 2022). "TRβ is a good prognostic factor in BRCA1-associated cancers and TRα is an adverse prognostic factor." (PMID 35160139, 2022). "Cancer cells with BRCA1/2 mutations treated with PARP inhibitors lead to cell cycle arrest and apoptosis through synthetic lethality, thus the PARP-1 protein has become an attractive target for the treatment of cancers in recent years." (PMID 35317687, 2022). "Germline mutations in BRCA1/2 are highly prevalence in breast cancer, ovarian cancer and many other types of cancer, including lymphoma, leukemia, melanoma, prostate, pancreatic, stomach, and colorectal cancer." (PMID 35719981, 2022).
cancer (continued). "Since HRD and inhibition of PARP are synthetically lethal, cancer patients carrying BRCA1 or BRCA2 mutations benefit from PARP inhibitor therapy." (PMID 35159019, 2022). "Germline mutations of the genes BRCA1/2 are related to increased cancer predisposition, and they account for approximately 14% of epithelial OC." (PMID 35645374, 2022). "Some degree of cancer worry is considered normal, and most BRCA1/2-PV carriers have declining cancer worry after gynaecological risk-reducing surgery." (PMID 34997316, 2022). "Point mutations within BRCA1/2 leading to coding sequence disruption depend on the mutation rate in cancer cells." (PMID 35205846, 2022). "In particular, PARP1- and PARP2-specific inhibitors are being used in combination with conventional anticancer drugs to promote synthetic lethality in cancer cells with BRCA1/2 mutations." (PMID 35269974, 2022). "Expression of X-linked inhibitor of apoptosis (XIAP) is increased in BRCA1-mutated cancers and high levels are associated with improved patient outcomes after platinum chemotherapy." (PMID 35501389, 2022). "This fact requires differentiation between patients with cancer and those with a high risk because the latter have a higher likelihood of a primary carcinoma, especially carriers of the BRCA1 mutation." (PMID 35834508, 2022). "We therefore propose that BRCA2 isoform switching represents a tumorigenic driver in BRCA1/2 mutation-associated cancers." (PMID 36344544, 2022). "Consistent with this, patients with familial breast, ovarian, prostate, pancreatic and other cancers often harbour heterozygous germline BRCA1/2 mutations." (PMID 35107878, 2022). "For 142 HRR genes including BRCA1/2, we analyzed the association of the level of HRDsum with mutation status pan-cancer and in each of the cancer types." (PMID 35681079, 2022). "Olaparib has been approved as a therapeutic agent for cancer patients harboring BRCA1/BRCA2 mutations." (PMID 35563432, 2022). "As is well-known, HRD including BRCA1/2 mutation is one biomarker to measure the genomic instability, a hallmark of human cancer." (PMID 36518306, 2022). "Docking studies for the target protein, breast cancer type-1 susceptibility protein, BRCA1 and phytocompounds (ligands) of S. torvum fruit were performed using PyRx software." (PMID 34643844, 2022). "Testing of patients with cancer for high penetrance breast-ovarian cancer susceptibility gene (CSGs) BRCA1, BRCA2 and PALB2 offers three potential benefits." (PMID 35868849, 2022). "The high penetrance of the BRCA1 gene was recognized early on in the course of BRCA1 characterization by analyses showing that mutation carriers have an increased lifetime risk of developing breast (40–85%) and/or ovarian (16–64%) cancers." (PMID 35432218, 2022). "The high cumulative genetic risks incurred by pathogenic BRCA1/2 variants paved the way for rapid founder variant testing as the first step to increase access to cancer genetic testing in South Africa and to reduce loss to follow-up." (PMID 36568162, 2022). "Carrier frequency of pathogenic variants in BRCA1 was 0.44% in 1 cancer type, 0.85% in 2 cancer types, and 0.69% in 3 cancer types." (PMID 35420638, 2022). "Despite the strong potency of PARPi in DSB repair-defective cancer cells, the resistance to PARPi-induced synthetic lethality has been reported in BRCA1/2-deficient and HRD tumor cells." (PMID 36497275, 2022). "Recently, data on the differences in cancer risk association in male patients with BRCA1 and BRCA2 pathogenetic variants have emerged." (PMID 35454911, 2022). "The patient underwent genetic testing by Invitae with a multi-cancer 84-gene panel, including BRCA1/2, which can detect most known cancer-causing variants (mutations)." (PMID 35847860, 2022). "Identifying these BRCA1/2 mutations is crucial to planning the treatment and follow-up of cancer patients." (PMID 36230639, 2022).
cancer (continued). "Overall, our results demonstrate that pyridostatin is a compound suitable for further therapeutic development, alone or in combination with paclitaxel and DNA‐PKcs inhibitors, for the benefit of cancer patients carrying BRCA1/2 mutations." (PMID 35107878, 2022). "The use of olaparib in cancer therapy is mainly based on its specific action in cells with BRCA1 and BRCA2 gene mutations." (PMID 35740913, 2022). "DSBs can be repaired by HR, but if HR is missing or defective in cancer cells, as in BRCA1 mutation-carrying cancers, the cell must use error-prone NHEJ, leading to genomic instability and cancer cell death." (PMID 36499000, 2022). "Dysfunction of BRCA1/2 leads to cancer susceptibility via the induction of chromosomal instability and mutagenesis." (PMID 35806485, 2022). "Studies have also revealed that BRCA1-deficient cancers are associated with greater numbers of tumor-infiltrating lymphocytes (TIL) than other cancers and with increased expression of immunomodulatory genes, including PDCD1 (PD-1), PD-L1, and CTLA420–22." (PMID 35304461, 2022). "RBBP8 interacts with tumor suppressor genes such as BRCA1 and the pRb family members through binding domains that are frequently mutated in human cancers." (PMID 36076047, 2022). "In a seminal study that comprehensively classified somatic point mutations and large-scale genomic alterations from 7042 cancers into 20 distinct mutational signatures, ‘signature 3′ was highly associated with BRCA1/2-inactivating mutations." (PMID 35163621, 2022). "These authors performed a genome‐wide CRISPR‐Cas9 synthetic lethal screen to identify genetic vulnerabilities in BRCA1/2‐deficient cancer cells." (PMID 35834102, 2022). "For example, BRCA1, which is involved in HR, has been found to be mutated at both germline and somatic levels, or epigenetically silenced in cancer." (PMID 36362142, 2022). "Consistent with the low number of average mutations per sample, we find that the EGFR-mut cancers conserved 16 genes related to DNA repair (e.g., BRCA1 and BRCA2)." (PMID 36612014, 2022). "A novel approach in the treatment of cancers characterized by the presence of BRCA1/2 mutations, such as ovarian and breast cancer, was also analyzed." (PMID 35342397, 2022). "Poly (ADP-ribose) polymerase (PARP) inhibitor, which inhibits single-strand DNA break compensation, can activate apoptosis in cancer cells with BRCA1/2 mutation and increase anti-cancer platinum sensitivity." (PMID 35954337, 2022). "The epidemiological evidence highlighted the ever-important value of a family history as a potential predictor of a positive test result, as 90% of patients with an actionable BRCA1/2 variant reported family members affected with BC and other cancer types." (PMID 35464868, 2022). "CST has been reported to promote PARP inhibitor sensitivity in BRCA1-deficient cancer cells, highlighting that it can be a potential therapeutic target." (PMID 35368664, 2022). "Mutations in BRCA1/2 have been found in a wide range of cancers, leading to the inactivation of the HR pathway." (PMID 36497275, 2022). "The sporadic cancer case harboring the BRCA1 variant was diagnosed with HGSC at the age of 45 years, and the variant was verified by bidirectional Sanger sequencing of their PBL DNA." (PMID 35456503, 2022). "This has been studied extensively in the preclinical and clinical setting in cancers harboring BRCA1/2 mutations, which induce homologous recombination deficiency (HRD), leading to a reliance on other compensatory DDR pathways such as BER and NHEJ." (PMID 36358724, 2022). "These genes can become altered, known as BRCA1/2 alterations or mutations, significantly increasing the cumulative lifetime risk for numerous cancers." (PMID 35933387, 2022).